BRAF (B-Raf proto-oncogene, serine/threonine kinase)
Diseases named in the same sentence as BRAF in open-access papers (continued):
Sharing a sentence is not in itself a finding about the gene and the disease.
cancer (continued). "To address this hypothesis, we built and compared multiple machine learning models from a publicly available RPPA dataset for 26 BRAF-V600E pan-cancer cell lines and identified protein signatures predictive of sensitivity to the FDA-approved BRAF inhibitor vemurafenib." (PMID 31672130, 2019). "They found that patients with CIMP-high cancers experienced a significantly low COAD-specific mortality, and that CIMP-high tumors were associated with a significant reduction in COAD-specific mortality, regardless of both MSI and BRAF status." (PMID 31781164, 2019). "Because BRAF is the immediate proximal regulatory component of the RAS signaling network and because MAPK pathway activation is a bona fide oncogenic feature in neoplastic cells, BRAF inactivation could address a wide variety of MAPK pathway-driven cancers." (PMID 31426419, 2019). "The expression of let-7f was not significant in cancer tissues with BRAF V600E." (PMID 29713312, 2018). "Currently, there are no approved targeted therapies for non-V600 BRAF mutant cancer patients." (PMID 29739364, 2018). "Thus, both BRAF and MEK inhibitors show similar biological effects on cancer cells." (PMID 29950679, 2018). "Specifically, a fundamental question as to how BRAF V600E and mutant TERT, which each apparently represents a different molecular system, are functionally bridged at the molecular level in cooperatively promoting human cancer aggressiveness remains to be answered." (PMID 29422527, 2018). "Similarly to BRAF mutant/MSI cancers, BRAF mutant/MSS cancers do not typically truncate APC but still show moderately frequent activation of the Wnt pathway." (PMID 30598662, 2018). "The BRAF mutant/MSS cancers have not been as thoroughly studied as the BRAF mutant/MSI cancers." (PMID 30598662, 2018). "Therefore, it could be suspected that this novel three-sites BRAF gene fusion also intervenes with the MAPK pathway, which may play an important role in not only MA but also in other malignant tumors." (PMID 30111351, 2018). "Based on these 19 drug-variant combinations, 4 out of 6 sensitive mutations in DEPO (KRAS G12V, BRAF V600E, NRAS Q61K, and KRAS G12D) were significantly associated with sensitivity to at least one of their paired drugs in both the cancer-type-specific and non-specific settings." (PMID 30053901, 2018). "Combination treatment of BRAF inhibitor and MEK inhibitor, dabrafenib and trametinib re-established the T cells population, suggesting combination treatment may be beneficial for the rebound immune profile in progressed cancer." (PMID 29455663, 2018). "To test this hypothesis, we probed the activity of BET/MEK inhibitor combinations in cancer cell lines with and without RAS pathway mutations (mutations in RAS, BRAF, or NF1), and with varying levels of sensitivity to GSK525762." (PMID 29674704, 2018). "In this respect, although the clinical outcome of RAS/BRAF WT mCRC has been improved in recent years for the integration of EGFR agents in the continuum of care, the antitumor efficacy of these drugs is transient and EGFR inhibitor-acquired cancer resistance occurs." (PMID 29137301, 2017). "Methylation may be contributing to gene silencing in a proportion of BRAF mutant cancers, but the large extent of absent protein expression indicates other mechanisms are also responsible for this." (PMID 25613750, 2015). "Epigenetic modification may be contributing to gene silencing in a proportion of BRAF mutant cancers and the large extent of absent protein expression indicates other mechanisms are also responsible for PRDM5 down-regulation." (PMID 25613750, 2015). "RTK-activated cancers, unlike BRAF V600E-activated cancers, may harbor lower levels of the ERK1/2 phosphatase, DUSP4." (PMID 26084293, 2015). "Interestingly the vast majority of cancers in both the BRAF mutant and BRAF wild type cancer cohorts lacked PRDM5 protein expression." (PMID 25613750, 2015).
cancer (continued). "A previous study has suggested that cell lines harboring the KRAS mutation such as HCT116 as well as the BRAF mutation are likely to be sensitive to CH5126766, whereas RAS-mutant cancer cells may not be sensitive to other MEK inhibitors." (PMID 25422890, 2014). "The remaining BRAF mutant cancers do not methylate MLH1 and are microsatellite stable (MSS)." (PMID 24651849, 2014). "Although group 1 was not an independent predictor of survival, we wondered whether this negative result was caused by some BRAF-mutant, MSI– cancers having poor survival." (PMID 23165447, 2013). "However, a set of BRAF-mutant, CIMP-high, microsatellite stable cancers also exists and the origins of this type of tumour are currently unknown." (PMID 23671423, 2013). "We found no BRAF mutations in BAN MSS CRC, although the absence of MSI cancers in the cohort may contribute to this observation." (PMID 23286373, 2013). "In BRAF mutant/MSS cancers, significantly increasing levels of overall CIN were found with advanced stages of presentation, suggesting that CIN may contribute to progression of this type of cancer." (PMID 23110075, 2012). "In contrast, for overall CIN and at all individual chromosomal regions, the BRAF wild type/MSS cancers showed comparable rates of CIN at early and late stages, and this suggests that CIN is important for initiation or early progression within this cancer subgroup." (PMID 23110075, 2012). "Sorafenib may target the VEGFR and other membrane receptors expressed on the particular cancer cells, whereas the MEK inhibitor would specifically suppress the Raf/MEK/ERK cascade which is abnormally activated by the BRAF oncogene or other mutant upstream signaling molecules." (PMID 23085539, 2012). "This phenomenon was somewhat supported by a recent study which found that BRAF mutations represented early events in thyroid carcinogenesis, whereas mutations of PIK3CA and AKT1 were latter events not found in the primary cancers, but in metastases or recurrent cancers." (PMID 22007340, 2012). "A similar but non-significant trend was observed in BRAF mutant cancers." (PMID 23110075, 2012). "DCC is subject to epigenetic silencing and may be targeted by this mechanism rather than deletion in BRAF mutant cancers." (PMID 23110075, 2012). "We hypothesized that although CIN may be mutually exclusive with MSI, it is not mutually exclusive with CIMP and may be common in BRAF mutant/MSS cancers." (PMID 23110075, 2012). "In a previous work we found that a pair of site-specific cAMP analogs (8-PIP-cAMP and 8-HA-cAMP), which, when used in combination, selectively activate PKA I, had a potent antiproliferative effect on two BRAF-positive carcinoma cell lines (ARO and NPA), but not on the BRAF-negative WRO cells." (PMID 21695205, 2011). "Of the 186 patients without germline P/LP variants and available cancer genomes–exomes, 41/186 patients had a somatic variant in the DNA damage response pathway (ATRX, ATM, PPM1D, POLE) and 21/186 had a variant in the MAPK-ERK pathway (BRAF, NF1, PTPN11, MAPK12)." (PMID 40072012, 2025). "Notably, suppression of UM cells was seen in the range of doses that by themselves are essentially non-toxic to cancers driven by activated BRAF and may even be protective to non-cancerous cells under certain stress conditions." (PMID 41154654, 2025). "miR-146b expression was higher in PTCs than in other cancers (mean fold change values ± SD: 27.14 ± 43.6 vs. 1.98 ± 3.1, p = 0.0135, respectively), and, among PTCs, it was significantly higher in BRAF-positive than in BRAF-negative cases (38.5 ± 49.2 vs. 3.2 ± 4.4, p = 0.0190)." (PMID 37686562, 2023).
cancer (continued). "Microsatellite instability and BRAF/IDH1 mutations were rare or absent events in our series and unrelated to the CIMP phenotype, suggesting that the mutational processes linked with CIMP phenotype in MPM may differ from those of other cancers." (PMID 36928603, 2023). "However, BRAF or MEK inhibitors are not suitable for all BRAF‐mutant cancers." (PMID 36254250, 2022). "Moreover, it was found that though ATG7 depletion alone could not reduce cancer cell viability, this depletion led to heightened sensitivity to the knockdown of BRAF and CRAF." (PMID 34830283, 2021). "Moreover, it is BRAF and not CRAF, ARAF, or KSR that is frequently mutated in cancer genomes." (PMID 35582307, 2021). "Even the detection of MLH1 promoter hypermethylation or of a BRAF mutation (in CRC) does not exclude definitively the possibility of LS, and it remains important to consider the results in light of the clinical data, i.e., the patient’s personal and family history of cancers." (PMID 33530449, 2021). "An estimation of BRAF V600E status in the initial course of the disease could not only help to avoid overtreatment in a patient with a less aggressive cancer phenotype (BRAF negative PTCs) but also to predict the treatment response in those with a BRAF positive status." (PMID 34070605, 2021). "Moreover, associations with other sonographically-alerting findings, such as marked hypoechogenicity, solid structure, taller-than-wide shape, and absence of halo microcalcifications and mixed-type non-increased vascularity were also demonstrated in BRAF V600E positive carcinomas." (PMID 34070605, 2021). "Therefore, the combination of SHP2 and MAPK inhibitors for treating KRAS or BRAF mutant cancers may not benefit all patients when FGFRs are involved in the feedback activation." (PMID 32076487, 2020). "Importantly, the chance to integrate cancer vaccines in future combinatorial immunotherapy regimens extends beyond checkpoint inhibitors to include immune costimulatory agonists (i.e., OX40 and 4-1BB), immunomodulatory agents, as well as selected inhibitors of oncogenic kinases (i.e., BRAF and MEK)." (PMID 33086492, 2020). "However, it has not been specifically approved for use against BRAF-mutant cancers." (PMID 30975211, 2019). "Although the oncogenic potential and resistance to RAF inhibitor of BRAF(ΔNVTAP) has been reported recently, whether all BRAF mutants with in-frame deletions of β3-αC loop are able to function as cancer drivers and their pharmacological characteristics are not clear." (PMID 29930381, 2018). "For unknown reasons, 25% do not silence MLH1 and become BRAF mutant MSS cancers." (PMID 29304767, 2018). "In addition, this study found residual presence of an SSA in approximately 30% of TSAs which suggests SSAs that do not methylate MLH1 could progress via a TSA to BRAF mutant/MSS cancer." (PMID 30598662, 2018). "In summary, the absence of BRAF and NRAS mutations in every carcinoma displaying NIS membrane staining at immunohistochemistry supports the assumption that the genetic background of tumors may be of major importance to SLC5A5 expression as well as to NIS targeting to the basolateral membrane." (PMID 29298843, 2018). "Finally, we also reviewed PIK3CA, CTNNB1, and ARID1A, as well as KRAS and BRAF, for somatic mutations in these genes have been reported to occur in EOC subtypes and corresponding cell lines most often representing other non-HGS subtype cancers." (PMID 26622941, 2015).
cancer (continued). "These cancers, through their heavily methylated phenotype have been found to methylate other inhibitors of the Wnt pathway such as DKK1 and AXIN2, which indicates epigenetic regulation of the Wnt pathway may be more prevalent in the BRAF mutant/MSI compared to other CRC subtypes." (PMID 25613750, 2015). "Retrospective analysis of pts treated with cetuximab or panitumumab at an Italian and a Swiss cancer center.Primary or secondary endpoints were not defined.PCR amplification with specific primers followed by automated sequencing by ABI PRISM 3730 was used to identify KRAS and BRAF sequence variants." (PMID 20972475, 2010). "Concerning ENO2, literature reports indicated upregulation in cancer rather than downregulation, as it occurred in our mutant transfected cells, but additional studies are needed to find any specific correlation of this subunit of the enolase in CRC and KRAS/BRAF mutations." (PMID 19087308, 2008). "Unlike EGFR and HER2 inhibitors that target receptor tyrosine kinases located on the cell surface, ALK, BRAF/MEK, and PI3K/AKT/mTOR inhibitors act on non-receptor kinases in intracellular signaling pathways critical for cancer cell proliferation and survival." (PMID 40872476, 2025). "Since BRAF inhibitors are more effective in SKCM, we measured prediction error in this cancer split by the drug non-responsive and responsive cases." (PMID 39304771, 2024). "Although Ki-67, p-MEK1/2, and p-ERK1/2 protein levels in vemurafenib-only group decreased compared with the placebo group in A375 cancer tissues, it failed to block the activation of RAS-MAPK signaling in BRAF wild-type CDX tissues." (PMID 36872366, 2023). "Although a high degree of selectivity was achieved in these cell lines, the majority of BRAF V600E-bearing cancers are heterozygous, and SJF-0628 has not been extensively tested in these cancer types due to ineffective responses to BRAF-targeted treatment." (PMID 38136350, 2023). "In the case of other cancers (EU-TIRADS- and BRAF-negative), the miRNA assessment was highly effective." (PMID 37686562, 2023). "Despite several BRAF inhibitors have emerged, unfortunately unlike other cancers, BRAF mutant CRC patients showed inefficient responses to these BRAF inhibitors." (PMID 35974387, 2022). "In OncoKB but not the Cancer Gene Census, amplifications of CDK4 and BRAF are annotated as oncogenic whereas amplification of KRAS is likely oncogenic." (PMID 34313788, 2021). "BRAF-mutant cancer cells are not sensitized to MEKi in the absence of SHOC2, which is consistent with signalling by oncogenic BRAF being independent of RAF dimerization and therefore of SHOC2 phosphatase function." (PMID 31182717, 2019). "Indeed, in bRAF (b-RAF proto-oncogene)-driven melanomas, JNK-cJun (cellular-Jun proto-oncogene) signalling has been revealed to contribute to tumour progression, suggesting that blocking JNK signalling may be of therapeutic benefit in at least some cancer types." (PMID 29861494, 2018).
cancer (continued). "In line with the complex genetic structure of MM, most of the mutations were detected only in single patient samples (e.g., NRAS, ATM, NTRK1, cMET, HER2, BRAF, IDH1, IDH2), and most of them were not targetable in MM and other cancers beyond clinical trials." (PMID 30021955, 2018). "We demonstrated previously that autocrine signalling through TGFBR1, is required for transformation of rodent fibroblasts by oncogenic BRAF, but did not investigate this dependence in human models of activated RAS/RAF-driven cancer." (PMID 27835901, 2016). "Molecularly, the CpG Island Phenotype (CIMP) was predominant in the BRAF mutant cohorts, particularly the BRAFmut/MSI cancers; whereas no BRAFwt/MSS cancers were CIMP high (p<0.0001)." (PMID 24651849, 2014). "Importantly, the drug concentrations used in these experiments are known to be effective against cancer cells that are driven by RAS, but not BRAF oncogenes." (PMID 41154654, 2025). "PI3K can be targeted with alpelisib or buparlisib, and while no results are available to date for combination use with BRAF inhibitors, they have been tested with the MEK inhibitors trametinib and binimetinib and demonstrated antitumor activity in cancer types such as ovarian cancer." (PMID 38275291, 2024). "Interestingly, it was found that the expression of miR-221 above the established threshold revealed all cases of cancer other than PTC and the largest fraction (80.0%) of BRAF-negative PTCs." (PMID 37686562, 2023). "First, our study comprised a small sample of patients with BRAF V600E-positive NSCLC from three academic hospitals in China, and the results may not apply to other cancer centers." (PMID 35814395, 2022). "This cross-sectional study assesses existing BRAF alteration classifications and the spectrum of coexisting alterations of RAS pathway genes and cancer types in which they occur using nonredundant cancer samples from cancer genomics databases." (PMID 33507258, 2021). "Additionally, depletion of CRaf but not BRaf in KRas mutant mice resulted in an inhibition of downstream ERK phosphorylation, an additional finding emphasizing the role of CRaf in KRas-driven cancer." (PMID 34680208, 2021). "The recent discovery that BRAF acts upstream of IKKα(p45) phosphorylation and activation in CRC cells, as well as other cancer types, which does not impact on NF-κB activation, might have important implications in this scenario." (PMID 35582445, 2020). "CD133 protein was expressed in a FRO cell line (BRAF status unknown) but not in a TPC cell line, and not in eight cell lines, including FRO-mBRAF and cancer-derived thyrospheres/tumors." (PMID 26973599, 2016). "This new class of inhibitors is not subject to the paradoxical activation seen with the BRAF-selective inhibitors, and may be more effective in RAS-mutant cancers." (PMID 27096871, 2016). "BRAF-mut with CIMP-H is seen in the majority of syndromic, nonsyndromic cancers, and MSI cancers." (PMID 22997602, 2012). "Overall patient survival assessed with Cox proportional hazard models, adjusted for stage, indicated that BRAF mutant/MSS cancers with CIN at the 18q and 5q loci, conferred significantly poorer outcomes compared to those BRAF mutant/MSS cancers without CIN at these loci." (PMID 23110075, 2012). "By contrast, 8-Cl-cAMP strongly inhibits cell growth also in the BRAF-negative WRO cells, suggesting that it may be effective in a broader range of cancer cells." (PMID 21695205, 2011).